MBOAT2 (membrane bound glycerophospholipid O-acyltransferase 2)
Diseases named in the same sentence as MBOAT2 in open-access papers (continued):
Sharing a sentence is not in itself a finding about the gene and the disease.
tumor (11 papers, 2021 to 2025). "Previous studies demonstrated that circRNAs were associated with angiogenesis and that circ-MBOAT2 acted as an oncogene in tumor growth." (PMID 38255868, 2024). "Using the ESTIMATE algorithm, we determined that higher levels of MBOAT2 are associated with greater tumor purity and lower immune scores, indicating that MBOAT2 overexpression may contribute to tumor progression and immunosuppression." (PMID 35571489, 2022). "Circum-MBOAT2 up-regulation correlated with tumor size, differentiation, TNM stage, and lymph node metastasis in NSCLC." (PMID 40369698, 2025). "The potential relationship between MBOAT2 level and tumor immunity was analyzed using the ESTIMATE algorithm, CIBERSORT algorithm, and single-sample gene set enrichment analysis." (PMID 35571489, 2022). "As shown with the ESTIMATE algorithm, the MBOAT2 level was positively related to tumor purity (Cor = 0.37, P = 3.8e − 07) but negatively correlated with the immune score (Cor = −0.38, P = 2.7e − 07)." (PMID 35571489, 2022). "In this research, we found circ-MBOAT2 silencing suppressed tumor progression and glutamine catabolism via downregulating GOT1 through sponging miR-433-3p." (PMID 33832516, 2021). "In vivo assay was performed to illustrate the impacts of circ-MBOAT2 silencing on tumor formation in vivo." (PMID 33832516, 2021). "Subsequently, the volume and weight of the forming tumors were smaller or lighter in sh-circ-MBOAT2 group than in sh-NC group, showing the repressive impact of circ-MBOAT2 silencing on tumor formation." (PMID 33832516, 2021). "miR-664b-3p downregulation impaired the anti-tumor effect of circ-MBOAT2 reduction on NSCLC cells." (PMID 40369698, 2025). "A high MBOAT2 level was obviously related to a higher histologic grade (P = 0.001) and recurring disease (P = 0.006), indicating that MBOAT2 may play a key role in tumor progression in PC." (PMID 35571489, 2022). "Notably, normal pancreatic exocrine glandular cells and exocrine glandular cells stain positive for MBOAT2, while tumor tissue is highly positive predominantly in tumor cells." (PMID 36685915, 2022). "Our present study demonstrated that MBOAT2 overexpression may inhibit tumor antigen processing and presentation and correlates with reduced infiltration of aDCs and pDCs." (PMID 35571489, 2022). "Furthermore, circ-MBOAT2 expression was dramatically decreased in the neoplasms from sh-circ-MBOAT2 group when compared with the tumors from sh-NC group, illustrating sh-circ-MBOAT2 was effective in downregulating MBOAT2 expression in the forming tumors." (PMID 33832516, 2021). "Furthermore, miR-433-3p was negatively related to circ-MBOAT2 in expression, and miR-433-3p inhibitors attenuated si-circ-MBOAT2-mediated impacts on tumor development and glutamine catabolism." (PMID 33832516, 2021). "In addition, rescue experiments were employed to illustrate the effects between miR-433-3p and circ-MBOAT2 or GOT1 on tumor evolution and glutamine metabolism." (PMID 33832516, 2021). "Additionally, circ-MBOAT2 knockdown upregulated cell apoptotic rate, and repressed tumor growth in vivo." (PMID 33832516, 2021). "However, the role of circ-MBOAT2 in tumor immune escape is still obscure." (PMID 40369698, 2025). "Furthermore, the influences of circ-MBOAT2 knockdown on tumor formation in vivo were unveiled." (PMID 33832516, 2021). "Furthermore, circ-MBOAT2 silencing repressed tumor formation in vivo." (PMID 33832516, 2021). "Circ-MBOAT2 expression was up-regulated in NSCLC, and reducing circ-MBOAT2 hampered NSCLC cell proliferation, EMT, immune escape, and tumor growth in vivo." (PMID 40369698, 2025). "Taken together, MBOAT2 overexpression may interact with KRAS activation, promoting tumor progression and inhibiting the antitumor effect of CD8+ T-cells in PC." (PMID 35571489, 2022).
tumor (continued). "Consequently, we speculated that MBOAT2 overexpression impairs the antitumor effect of TILs, especially of CD8+ T-cells, through suppressing the tumor antigen presentation by DCs (e.g., aDCs and pDCs)." (PMID 35571489, 2022). "However, the biological role and mechanism of MBOAT2 in PC, especially whether MBOAT2 has an impact on tumor immunity, are not clear and need further investigation." (PMID 35571489, 2022).
MBOAT2 also shares sentences with these, for which no sentence is quoted: adrenocortical carcinoma (3 papers); bladder urothelial carcinoma (2); cardiomyopathies (2); mesothelioma (2); multiple sclerosis (2); paraganglioma (2); adrenomyeloneuropathy (1); bladder cancer (1); breast invasive carcinoma (1); cholangiocarcinoma (1); diffuse large B-cell lymphoma (1); endometrial carcinoma (1); glioma (1); head and neck squamous cell carcinoma (1); hepatocellular carcinoma (1); intrahepatic cholangiocarcinoma (1); kidney chromophobe (1); lung adenocarcinoma (1); lymphoid neoplasm (1); malaria (1); non-small cell lung carcinoma (1); osteosarcoma (1); pancreatic adenocarcinoma (1); prostate adenocarcinoma (1); Sepsis (1); skin cutaneous melanoma (1); squamous cell carcinoma (1); thymoma (1); urothelial carcinoma (1); uterine corpus endometrial carcinoma (1).